PPARG (peroxisome proliferator activated receptor gamma)
Diseases named in the same sentence as PPARG in open-access papers (continued):
Sharing a sentence is not in itself a finding about the gene and the disease.
tumor (continued). "However, the role of PPARG in tumor initiation remains highly intricate and is influenced by environmental factors." (PMID 38044948, 2023). "In addition to PPARγ’s role in tumor tissue and ferroptosis that ocurrs within, its importance also expands to edema." (PMID 37554158, 2023). "In addition, PPARγ agonists have been found to inhibit tumor proliferation, invasion, and angiogenesis." (PMID 37064872, 2023). "We next examined the integrity of the PPARγ program in tumor specimens." (PMID 37816052, 2023). "Moreover, immunohistochemical (IHC) analysis of tumor tissues from PPARG KO versus WT mice revealed a significant decrease in cell proliferation and microvessel density in the PPARG KO mice." (PMID 37100807, 2023). "Additionally, the activation of PPARG has demonstrated anti-inflammatory properties by suppressing the production of pro-inflammatory cytokines and modulating the tumor microenvironment (TME)." (PMID 38044948, 2023). "The role of PPARα/γ expression in tumor cells for response to tumor tissue editing approaches remains open, especially as metronomic chemotherapy may enhance PPARγ expression in stress response to metronomic chemotherapy." (PMID 38273846, 2023). "In mouse xenograft models, early intervention with rosiglitazone, a PPARγ agonist, demonstrated significant antitumor effects; however, following the development of a palpable tumor, the antitumor effects of rosiglitazone were negated by the repression of PPARγ in the mouse stroma." (PMID 37816052, 2023). "Previous findings suggest a pivotal role of PPARγ in tumor progression." (PMID 37770940, 2023). "TNF-a inhibits PPARγ activation in tumor and tumor-infiltrating macrophages." (PMID 37190200, 2023). "However, there remains uncertainty regarding the precise procedures and pathways through which PPARG influences tumor development, leading to a poor prognosis." (PMID 38044948, 2023). "A potent PPARγ activator, rosiglitazone, demonstrated antitumor activities when administered early in the progression of mouse mammary xenograft tumors but did not exhibit these activities when treatment was begun following the formation of a palpable tumor." (PMID 37816052, 2023). "The use of PPARγ inhibitors attenuates the pro-inflammatory effect of M1 TAMs and inhibits the secretion of pro-tumor cytokines by M2 macrophages to achieve the goal of inhibiting tumor progression." (PMID 37004014, 2023). "Given that PPARγ was suppressed in stromal cell types by tumor-secreted factors in our in vitro models, we hypothesized that tumor development in a mouse xenograft model would limit the antitumor efficacy of rosiglitazone, a potent PPARγ agonist." (PMID 37816052, 2023). "In addition, we identified a role for PPARγ in opposing the transition of pericytes toward a tumor-supportive myofibroblast phenotype." (PMID 37816052, 2023). "Furthermore, the proliferation of BM requires the activation of peroxisome proliferator-activated receptor gamma (PPARγ) situated within the tumor nucleus, forming heterodimers with RXR to trigger related genes." (PMID 38104104, 2023). "In recent years, more studies have shown that PPARG protein plays an important role in inflammation or epithelial–mesenchymal transition-related biological processes, including fibrosis, tumor development, and processes regulating TGF-β1 gene transcription and inflammation causing tissue fibrosis." (PMID 37569334, 2023). "In the vehicle-treated MDA-MB-468 controls, which contained invasive lesions large enough to evaluate adjacent stromal cells, we observed a significantly lower percentage of Pparγ+ adipocytes near invading tumor cells compared to unaffected regions of the mouse mammary gland." (PMID 37816052, 2023). "This PPARγ/PLZ-Srebf1-cholesterol pathway was found to contribute to anti-tumor immunity." (PMID 37917548, 2023).
tumor (continued). "Among the PPARs, PPARγ activation has been demonstrated to induce terminal differentiation and inhibit cell growth and inflammation in numerous malignant cell types and murine tumor models, suggesting that PPARγ agonists may act as tumor suppressors." (PMID 37048080, 2023). "Indeed, a significant body of evidence supports the role of PPARγ as a tumor suppressor in various types of cancer." (PMID 37645246, 2023). "Similarly, PPARγ activation has been found to suppress cell proliferation, induce cell differentiation, and inhibit tumor invasiveness in various cancer types." (PMID 37645246, 2023). "In an effort to further illuminate the significance of CD36 repression in the development of a tumor-supportive stroma, we uncovered a broader impairment of PPARγ-activated transcriptional programs affecting several stromal cell types, including pericytes, ECs, and adipocytes." (PMID 37816052, 2023). "Thus, tumor cell signaling can impair the PPARγ-dependent, anti-tumorigenic state of certain stromal cells found in healthy tissues." (PMID 37816052, 2023). "Overall, the immune-regulatory function of PPARγ and its ligands may be useful to fine-tune immune responses in tumor-bearing hosts." (PMID 37686465, 2023). "The anti-tumor functions of PPARα and PPARγ are currently inconclusive and controversial." (PMID 37033970, 2023). "It has been reported that the activation of PPARγ with its agonists could improve the anti-tumor responses and superior tumor control along with IFN-γ production from tumor-infiltrated NKT cells." (PMID 37158883, 2023). "A tumor-promoting role for PPARγ has been suggested in a variety of cancers as well." (PMID 35395810, 2022). "The inhibition of PPARγ reduces lipid synthesis and tumor growth." (PMID 35954274, 2022). "Numerous studies show that PPARγ has a tumor-promoting effect." (PMID 36359869, 2022). "Following therapeutic editing of tumor tissue with PPARγ agonists, inflammation control and enhanced immunosurveillance may be achieved." (PMID 35814409, 2022). "Additionally, in metastatic brain tumors, PPARγ is activated and contributes to metastatic spreading of the tumor cells due to the generation of lipid-derived endogenous PPAR activators from surrounding astrocytes." (PMID 35954274, 2022). "Autophagy can either suppress or promote tumor growth, and deducing that the induction of autophagy in cancers via PPARγ modulation might be beneficial is, consequently, erroneous." (PMID 35954274, 2022). "In CRC, ILC2s suppress tumor by producing IL-9, but maintain pro-tumor effect by expressing PPARγ." (PMID 35720302, 2022). "We observed that GATA4, AGR2, and PPARG were significantly underexpressed in tumor samples." (PMID 35069736, 2022). "Studies have shown that PPARγ can inhibit VEGF transcription-induced tumor angiogenesis by binding to the receptor responsive element (PPRE) in the VEGF promoter region in vitro, decrease the VEGF receptor expression in vascular endothelial cells, and suppress tumor angiogenesis." (PMID 35341213, 2022). "PPARγ therefore could serve as a potential target to modulate cell cycle to arrest the tumor growth in GBM." (PMID 36362294, 2022). "The situation might be even more complex as truncated isoforms of PPARγ might further fuel the metastasis-promoting actions of tumor stromal cells." (PMID 35954274, 2022). "PPARγ functions as a tumor suppressor in colon, lung, pancreatic, and breast cancers." (PMID 35395810, 2022). "Similarly, PPARγ agonists play a significant role in fighting against tumors, among others, by activating various signaling pathways to cancer cells and tumor stem cells." (PMID 35743814, 2022). "PPARγ regulates whole-body glucose homeostasis and insulin sensitivity, and currently, studies have focused on its involvements in inflammation, lipid metabolism, and tumor development, particularly in the context of CC." (PMID 35565236, 2022).
tumor (continued). "It indicated either activated PPARγ or truncated PPARγ could promote the pro-tumor effect of TAMs, but the further investigation should be carried out." (PMID 35392570, 2022). "In addition, tumor tissue showed an increase in heparanase, MMP9, PPARγ, and IFNγ, while non-tumor adjacent tissue showed an increase in E-cadherin and COX2 and a decrease in IL-4R." (PMID 36139645, 2022). "In addition, researchers found high expression of peroxisome proliferation-activated receptor gamma (PPARγ) in TUM-Treg cells (Treg cells extracted from the tumor bed)." (PMID 35251009, 2022). "In our study, exposure to 1 μM As3+ decreased the expression of PPARγ and since PPARγ plays a role in urothelial differentiation, a decrease in its expression could potentially increase the growth of the tumor cells." (PMID 36293167, 2022). "FABP4 overexpression inhibits tumor growth through the activation of PPARγ." (PMID 36532833, 2022). "We further assessed the role of PPARγ in suppressing tumor growth through modulation of STAT3." (PMID 36362294, 2022). "Our results indicate that PPARγ acts as a tumor suppressor by upregulating PTEN transcription." (PMID 36364935, 2022). "Interestingly, PPARγ protein expression level significantly dependent to the tumor grade (OR = 1.22, CI = 1.10–1.36, P-value < 0.0001)." (PMID 35922782, 2022). "The tumor suppressor PTEN can be positively regulated by PPARγ." (PMID 36364935, 2022). "The PPARγ protein could predict malignant tumor features including tumor grade, metastasis and recurrence significantly." (PMID 35922782, 2022). "The role of PPARγ as a tumor suppressor in CRC has been documented." (PMID 34889713, 2021). "In addition, we identified the degree of tumor mutational burden of BCRA and examined the relationship between PPARG and TMB." (PMID 34567087, 2021). "Additionally, recent work has implicated peroxisome proliferator-activated receptor gamma (PPARγ) activation in the regulation of TAM tumor response." (PMID 34483843, 2021). "Additionally, the gene-knockdown assay in HPAC and SW1990 cell lines was performed to further verify the function of PPARγ in regulating tumor cell survival." (PMID 35186942, 2021). "Unlike CAFs, the activation of PPARα and PPARγ in macrophages favors an anti-inflammatory tumor-associated macrophage (TAM) phenotype." (PMID 33946986, 2021). "Although its effect on the tumor is unknown, tomelukast could target the PPARα and PPARγ to regulate carbohydrate and lipid metabolism, and exert an anti-inflammatory action." (PMID 34966691, 2021). "When PPARG expression from in vivo experiments is compared, it does in fact appear that OE19 tumours have significantly higher PPARG expression than NTS tumours, which could account for the elevated AKT3 levels observed in OE19 tumours." (PMID 33654198, 2021). "Interestingly, growing evidence suggests that PPARγ functions as a tumor suppressor in several tumors, including breast carcinoma." (PMID 34067944, 2021). "The low expression of PPARG in the tumor and declining of its anti-tumor function could be due to the BRCA development and TMB accumulation." (PMID 34567087, 2021). "The feedback regulation of PPARγ by 15-LOX-2 was determined by overexpressing 15-LOX-2 in tumor cells with high levels of PPARγ and observing a concentration-dependent downregulation of PPARγ with increasing amounts of 15-LOX-2, an effect enhanced by coincubation with 15-S-HETE." (PMID 33799988, 2021). "Exploring the molecular mechanism subserving the action of PPARG may thus provide a novel anti-tumor treatment strategy for RMS." (PMID 35187064, 2021). "However, as recently reviewed by us, the role of PPARγ as a tumor suppressor in the breast cancer microenvironment needs to be fully understood for further investigations." (PMID 34067944, 2021). "In recent years, EPA has been proven to be a natural ligand for PPARγ, which may explain its anti-tumor effect." (PMID 37073266, 2021).
tumor (continued). "The ability of telmisartan, an AT1R blocker and a peroxisome proliferator-activated receptor gamma (PPARγ) agonist, to inhibit EC cell proliferation and tumor growth in nude mice adds further evidence to such hypotheses." (PMID 34358075, 2021). "For example, PPARγ could inhibit the development of lung adenocarcinoma through the regulation of tumor cell proliferation and transmission-related molecules." (PMID 33777130, 2021). "PPARγ levels are inversely correlated with tumor size, grade and TNM staging." (PMID 34631530, 2021). "Previous studies had shown that PPARγ activation by ligands or overexpression may either enhance or inhibit tumor growth depending upon the tumor type and oncogenic driver." (PMID 33946495, 2021). "Clinically, the notion that PPARγ could function as a tumor suppressor was reinforced by large epidemiological studies which observed that diabetic patients receiving thiazolidinediones had up to ~33% lowered risk for developing certain malignancies." (PMID 34580286, 2021). "Recently, substantial evidence indicates that PPARγ has the characteristics of a tumor suppressor." (PMID 37073266, 2021). "The tumor suppressing property of PPARγ remains controversial." (PMID 33802010, 2021). "Moreover, diminished ligand activation of PPARγ through the constitutive expression of Notch1 induces adipocyte de-differentiation and tumor-like manifestations." (PMID 33946986, 2021). "Although Pparγ has been implicated in the regulation of cellular growth, the role of endogenous Pparγ1 in the growth of mammary tumors and the impact on the anti-tumor immune response was not previously known." (PMID 33946495, 2021). "Previous studies demonstrated that PPARγ may either enhance or inhibit tumor growth depending upon the tumor type and oncogenic driver." (PMID 33946495, 2021). "Lastly, genetic ablation of PPARγ in ILC2s significantly suppresses tumor growth in vivo." (PMID 33953160, 2021). "TGFB1, IL1B, IL10, IL6, PTGS2, and PPARG closely interacted with the tumor microenvironment." (PMID 34394377, 2021). "Mechanistically, the transcriptional activities of STAT6 downstream of IL-4, and of the peroxisome proliferator-activated receptor Gamma (PPARγ) in conjunction with its co-activator PPARγ-coactivator-1beta (PGC-1β), are key for the differentiation and activation of tumor-associated myeloid cells." (PMID 34831183, 2021). "This function of PPARG allows for the provision of energy (ATP) which may fuel tumour growth and progression in PC." (PMID 33654198, 2021). "Regarding the dual role of PPARG gene played in the occurrence and development of tumors, we believe it may be related to multiple factors involved in tumor types and tumor progression in a specific environment." (PMID 34023860, 2021). "PPARγ has tumor-suppressive and oncogenic effects in several cancers." (PMID 34775964, 2021). "Next, we investigated the relationship between PPARG and the tumor immune microenvironment." (PMID 34567087, 2021). "In addition, the nuclear PPARγ expression level was significantly related to tumor size (p = 0.0105)." (PMID 35186942, 2021). "Accordingly, PPARα and PPARγ are considered tumor suppressor genes which inhibit tumor progression." (PMID 34109128, 2021). "In conclusion, even though the activation and expression of PPARs in HCC development continues to be controversial, in recent years, complementary therapies have been developed that mainly involve PPARα and PPARγ-activation, sensitizing tumor cells to traditional anticancer treatments used in HCC." (PMID 34361064, 2021). "Several in vitro and in vivo studies have suggested that PPARγ is effective as a tumor suppressor." (PMID 33802010, 2021). "A decreased number of gene copies was also widely observed in EBV(+) LCs, including tumor-associated genes such as zinc finger and BTB domain-containing 16 (ZBTB16), peroxisome proliferator activated receptor gamma (PPARG), and transforming growth factor beta receptor 2 (TGFBR2)." (PMID 34064727, 2021).
tumor (continued). "In addition, recent data showed that the expression level of PPARγ in skeletal muscles of tumor-bearing mice was markedly decreased, suggesting that it involved in the process of muscle atrophy." (PMID 34093209, 2021). "Indeed, dietary supplementation with ω-3 PUFAs has been reported to increase PPARγ protein expression, which was concomitant with a reduction of tumor burden in rats with induced mammary carcinogenesis." (PMID 32937951, 2020). "THC increased the activity of PPARγ in HCC cells, and the pharmacological inhibition of PPARγ inhibited the anti-tumor action of THC in these cells, both in vitro and in vivo, indicating that the anti-proliferative actions of THC in HCC cells are influenced by PPARγ-dependent pathways." (PMID 32708138, 2020). "Combination of radiotherapy with the PPARγ agonist rosiglitazone enhanced the effectiveness of radiotherapy against tumor angiogenesis, distant metastasis formation, and tumor recurrence in animal models with subcutaneous breast or colon cancer cell implantation." (PMID 32785018, 2020). "PPARG is a nuclear receptor that functions as a transcription factor to regulate the expression of several genes involved in lipid metabolism, glucose homeostasis, and tumor progression in many tissues." (PMID 32850439, 2020). "In contrast, overexpressing PPARγ‐S273A abrogated stemness transformation in vitro and in vivo, which resulted in the marked suppression of tumor growth and pulmonary metastasis." (PMID 33240752, 2020). "Decreased expression of PPARγ has been observed in many tumor types." (PMID 33194695, 2020). "However, with mixed bone marrow chimeric mice in which PPARγ was specifically deleted in iNKT cells, we confirmed that PPARγ expression in iNKT cells was required for the anti-tumor efficacy of PIO and αGC treatment." (PMID 31974378, 2020). "In this study, we hypothesize that PPARG may play roles in HSCC chemotherapy by influencing the tumor cell chemosensitivity." (PMID 32373170, 2020). "PPARG has been suggested as a target for chemoprevention in head and neck cancer prevention, which was based on consistent evidence from investigations of human tumor cell line studies, epidemiological analysis, and animal carcinogenesis models." (PMID 32373170, 2020). "A receiver operating characteristic (ROC) curve was used to evaluate the diagnostic value of PPARγ and ERRα mRNA expression to further determine whether PPARγ and ERRα could serve as tumor markers." (PMID 33197888, 2020). "In contrast to PPARβ/δ, most studies identified PPARγ as an inhibitor of tumor angiogenesis." (PMID 32785018, 2020). "Further in vivo studies involving orthotopic and heterotopic xenograft mouse models confirmed the therapeutic efficacy of targeting PPARγ; compared to control mice, those that received ligand treatment exhibited longer survival as well as decreased tumor burden." (PMID 32280134, 2020). "While pioglitazone showed its anti-inflammatory effects to be reliant on AnxA1, it is known pioglitazone has other effects that are PPARγ-independent, such as induction of migration of vascular smooth muscle cells and inhibition of proliferation of tumor cells." (PMID 33519451, 2020). "Peroxisome proliferator activated receptor-γ (PPARγ) is widely expressed in various tumours and cell lines, thus this receptor has become a target for developing new anticancer drugs that can take advantage of the antiproliferative effects mediated through PPAR." (PMID 32170185, 2020). "Interestingly, synthetic PPARγ agonist rosiglitazone reduced secretion of M1 pro-inflammatory and pro-tumor M2-cytokines." (PMID 33352766, 2020). "PPARγ is known to exert profound effects on both tumor cells and host immune cells." (PMID 32226299, 2020). "In PCa, PPARγ is overexpressed and its levels are positively correlated with tumor grade and stage." (PMID 33031638, 2020).